NIBAN1 (niban apoptosis regulator 1)
Description:
Regulates phosphorylation of a number of proteins involved in translation regulation including EIF2A, EIF4EBP1 and RPS6KB1. May be involved in the endoplasmic reticulum stress response (By similarity).
Synonyms: C1orf24; FAM129A; NIBAN; GIG39
Tractability: Antibody: its Gene Ontology location is reachable by antibodies, with high confidence. PROTAC: ubiquitination databases record sites on it.
Gene: Protein-coding gene on chromosome 1 (184,790,724 to 184,974,611, reverse strand). Ensembl gene ENSG00000135842.
Subcellular location: Cytoplasm; Membrane
Subcellular location (Human Protein Atlas): Cytosol; Plasma membrane
Gene Ontology:
Molecular function: protein binding
Biological process: negative regulation of protein phosphorylation; positive regulation of protein phosphorylation; positive regulation of translation; response to endoplasmic reticulum stress
Cellular component: cytoplasm; cytosol; extracellular exosome; membrane
Genetic constraint (gnomAD): Loss-of-function variants: 63 observed, 64.14 expected, observed/expected ratio (o/e) 0.98, 90% interval 0.8 to 1.21. The upper end of that interval is the gene's LOEUF score, 1.21, which puts it in group 5 of 6, group 1 being the genes least tolerant of losing a copy. Missense variants: 1,098 observed, 1,129.8 expected, observed/expected ratio (o/e) 0.97, 90% interval 0.92 to 1.02. Synonymous variants: 427 observed, 427.41 expected, observed/expected ratio (o/e) 1, 90% interval 0.92 to 1.08.
Homologues: Orthologues: chimpanzee NIBAN1 (99% identical), macaque NIBAN1 (95% identical), pig NIBAN1 (78% identical), dog NIBAN1 (77% identical), rat Niban1 (72% identical), mouse Niban1 (72% identical), rabbit NIBAN1 (58% identical), zebrafish niban1b (35% identical), zebrafish niban1a (29% identical). Paralogues in human: NIBAN2 (27% identical), NIBAN3 (18% identical).
Diseases named in the same sentence as NIBAN1 in open-access papers:
NIBAN1 is named in the same sentence as 41 diseases in open-access papers, as found by Europe PMC text mining. Sharing a sentence is not in itself a finding about the gene and the disease. The quoted sentences say what the papers report.
thyroid cancer (9 papers, 2011 to 2025). "On the other hand, in thyroid cancer cell lines, NIBAN1 silencing increased autophagic flux, suggesting that NIBAN1 inhibits autophagy during the thyroid carcinogenic process." (PMID 35517496, 2022). "In thyroid carcinoma, the expression of NIBAN1 is highly elevated under nutrient/growth factor deprivation." (PMID 35281857, 2022). "Niban1 is highly expressed in some cancer cells and may serve as a prognostic marker for certain cancers, such as renal and thyroid carcinoma." (PMID 37583898, 2023). "NIBAN1 protein is highly expressed in multiple cancers such as renal, colorectal, and thyroid cancer and may play an important role in cell survival during cellular stress such as ultraviolet irradiation cell migration and proliferation, cell autophagy and immune microenvironment." (PMID 40186177, 2025). "Although NIBAN1 is involved in the carcinogenesis of renal and thyroid cancer 14, 15, its role in cancer drug resistance has not yet been reported." (PMID 35281857, 2022).
thyroid (5 papers, 2011 to 2024). "Overall, these results, together with the functional experiments from our group, provide a global genetics picture of NIBAN1 expression in thyroid carcinogenesis and demonstrate a strong association between NIBAN1 overexpression and poor clinical features and more aggressive phenotype." (PMID 38425426, 2024). "Remarkably, the data suggest that BRAFV600E mutation might influence NIBAN1 expression in an MYC-dependent manner during the thyroid carcinogenic process." (PMID 38425426, 2024).
renal carcinoma (3 papers, 2019 to 2023). A carcinoma arising from the epithelium of the renal parenchyma or the renal pelvis. "Niban1 is mainly expressed in the cytoplasm and is used as a candidate marker for the development of renal tumors, especially early-stage renal carcinoma." (PMID 37583898, 2023).
thyroid tumor (3 papers, 2011 to 2024). A benign or malignant neoplasm affecting the thyroid gland. "According to the results demonstrated herein, NIBAN1 expression seems to be associated with histopathological characteristics and aggressiveness of thyroid tumors." (PMID 38425426, 2024). "Our study demonstrates, for the first time, that NIBAN1 expression varied according to thyroid tumor subtypes, presence of BRAFV600E mutation, worse clinical features, and aggressive phenotype." (PMID 38425426, 2024).
colon carcinoma (2 papers, 2018 to 2022). "CBFβ and RUNX2 are others transcription factors that activate NIBAN1 expression in colon cancer." (PMID 35517496, 2022).
prostate carcinoma (2 papers, 2021 to 2022). A carcinoma that arises from epithelial cells of the prostate gland. "In prostate cancer, NIBAN1 expression is regulated by androgen receptor (AR)." (PMID 35517496, 2022). "In prostate cancer, NIBAN1 is rapidly activated in response to ER stress by ATF4, either by stimulating eIF2α phosphorylation, via PERK, or by inhibiting eIF2α phosphorylation directly, via NIBAN1." (PMID 35517496, 2022).
bladder cancer (1 paper, 2022). "Our analysis revealed that the focal adhesion signaling pathway is the most enriched signaling pathway in NIBAN1-high bladder cancer." (PMID 35281857, 2022). "Manipulation of NIBAN1 expression affected the chemosensitivity to GEM in bladder cancer cell models." (PMID 35281857, 2022). "We conducted Gene Set Enrichment Analysis on The Cancer Genome Atlas bladder cancer dataset to identify the downstream signaling pathways regulated by NIBAN1." (PMID 35281857, 2022). "Taken together, these findings confirm the role of NIBAN1 as a potential regulator of GEM resistance in bladder cancer in vivo." (PMID 35281857, 2022). "Our findings suggest that NIBAN1 might regulate FAK signaling activation to promote GEM resistance in bladder cancer." (PMID 35281857, 2022). "We showed that NIBAN1 might modulate activation of the FAK signaling pathway to promote GEM resistance in bladder cancer cells." (PMID 35281857, 2022). "Moreover, NIBAN1 also regulated focal adhesion/focal adhesion kinase (FAK) signaling activation in bladder cancer cell lines." (PMID 35281857, 2022). "We investigated the effect of NIBAN1 on FAK signaling activity in bladder cancer cell models." (PMID 35281857, 2022). "Our present findings suggest that NIBAN1 might be a novel regulator of GEM resistance in bladder cancer, which may help develop novel therapeutic strategies in the future." (PMID 35281857, 2022). "Therefore, NIBAN1 might regulate FAK signaling activation to promote GEM resistance in bladder cancer, and targeting NIBAN1/FAK signaling could potentially sensitize bladder cancer cells to GEM chemotherapy." (PMID 35281857, 2022). "Targeting NIBAN1/FAK signaling may help sensitize bladder cancer cells to GEM treatment." (PMID 35281857, 2022). "Therefore, NIBAN1 might regulate FAK signaling activation to promote GEM resistance in bladder cancer cells." (PMID 35281857, 2022). "Our in vivo studies demonstrated that knockdown of NIBAN1 disrupted FAK signaling and sensitized GEM-resistant bladder cancer cells to GEM treatment." (PMID 35281857, 2022). "Therefore, NIBAN1 might be a novel regulator of GEM resistance in bladder cancer." (PMID 35281857, 2022). "Similar to NIBAN1 findings, knockdown of FAK also markedly attenuated GEM-resistant phenotypes in bladder cancer cells." (PMID 35281857, 2022). "Furthermore, our studies in in vitro cell line models showed that manipulation of NIBAN1 expression affected the chemosensitivity to GEM in bladder cancer cell models, suggesting that NIBAN1 might serve as a potential regulator of GEM resistance in bladder cancer." (PMID 35281857, 2022). "In vivo studies demonstrated that knockdown of NIBAN1 disrupted FAK signaling and sensitized GEM-resistant bladder cancer cells to GEM treatment." (PMID 35281857, 2022). "In addition, we showed that NIBAN1 could regulate FAK and its downstream SRC/AKT signaling activation in bladder cancer cell line models." (PMID 35281857, 2022). "Therefore, NIBAN1 might be involved in the regulation of GEM resistance, which needs to be functionally validated in bladder cancer cell models." (PMID 35281857, 2022).
cardiomyopathy (1 paper, 2023). A disease of the heart muscle or myocardium proper. "Significant differential imbalance between all four phenogroups was found for several SNPs located in genes with known cardiomyopathy links other than DCM such as posterior myocardial infarction, the top 5 hits were EZH1, NIBAN1, C7, CDIN1, and ADPRHL1." (PMID 36631531, 2023).
cyst (1 paper, 2023). A sac-like closed membranous structure that may be empty or contain fluid or amorphous material. "Whether Niban1 regulates cyst cell formation through the same pathways as in cancer cells remains to be verified." (PMID 37583898, 2023).
lung carcinoma (1 paper, 2022). "Also, in lung cancer, NIBAN1 overexpression was associated with advanced staging, lymph node metastasis, and poor survival rates." (PMID 35517496, 2022).
Renal cyst (1 paper, 2023). A fluid filled sac in the kidney. "Similar to the findings in NPHP1 mice, Niban1 expression was confined to the renal cyst cells and dilated tubular cells of NPHP1 patients and absent from the uninvolved tubular cells of NPHP1 patients and normal tubular cells of control patients." (PMID 37583898, 2023). "To study whether Niban1 is also expressed in the renal cyst cells of NPHP1 patients, we performed immunohistochemistry and immunofluorescence on paraffin-embedded specimens of kidney biopsy tissue from 3 NPHP1 patients and 3 control patients." (PMID 37583898, 2023). "We concluded that Niban1 is a specific molecular marker of NPHP1 patient renal cyst cells." (PMID 37583898, 2023).
tumor (17 papers, 2013 to 2025). "All these data demonstrate the NIBAN1 roles in cell survival, and consequently, its biological functions associated with tumor progression." (PMID 35517496, 2022). "Furthermore, NIBAN1 expression also appears to be associated with the mutational profile of the tumor." (PMID 38425426, 2024). "As a result of the cellular characteristics of these neoplasia, it has been suggested that NIBAN1 may be closely associated with altered mitochondrial functions in pre-neoplastic conditions and in oxyphilic tumors." (PMID 35517496, 2022). "Considering that the tumor microenvironment can recruit different types of immune cells, the fractions of infiltrating immune cells between NIBAN1-Low and NIBAN1-high were predicted using 22 immune cell types." (PMID 38425426, 2024). "The absence of expression in normal rat/human kidneys and strong expression in tumor suggests an inverse relationship between NIBAN1 expression and progression of renal carcinogenesis." (PMID 35517496, 2022). "However, NIBAN1 knockdown effectively suppressed the tumor growth after GEM treatment compared with Scr (PBS), Scr (GEM), or shNIBAN (PBS) group." (PMID 35281857, 2022).
cancer (15 papers, 2011 to 2025). A tumor composed of atypical neoplastic, often pleomorphic cells that invade other tissues. "FAM129A (also known as NIBAN1 or Niban apoptosis regulator 1) encodes a protein that is highly expressed in cancer." (PMID 34088951, 2021). "In this sense, the comprehension of the NIBAN1 function, in many diseases and cancer progression, is fundamental for the management of cell stability as well as both diseases and cancer treatments." (PMID 35517496, 2022). "Although NIBAN1 has been described more than 20 years ago, its roles in cancer and other cellular contexts still need to be elucidated." (PMID 35517496, 2022). "Highly increased NIBAN1 expression was observed in a number of GEM-resistant cancer cell lines and in post-IGC recurrent NMIBC specimens." (PMID 35281857, 2022). "The biological effects of NIBAN1 upregulation in human cancer." (PMID 35517496, 2022). "Consistent with this hypothesis, we observed highly increased expression of NIBAN1 in GEM-resistant cancer cell lines and in post-IGC recurrent NMIBC specimens." (PMID 35281857, 2022). "PADI4 inhibitor treatment in cancer cells downregulated four genes related to metastatic cancer phenotypes: Laminin Subunit Gamma 2 (LAMC2), C-X-C Motif Chemokine Ligand 8 (CXCL8), Niban Apoptosis Regulator 1 (FAM129A), and Pleckstrin 2 (PLEK2)." (PMID 36233212, 2022).
NIBAN1 also shares sentences with these, for which no sentence is quoted: papillary thyroid carcinoma (3 papers); cervical carcinoma (2); clear cell renal cell carcinoma (2); thyroid nodule (2); adrenocortical carcinoma (1); aneurysm (1); asthma (1); atherosclerosis (1); benign prostatic hyperplasia (1); breast carcinoma (1); Cirrhosis (1); clear cell carcinomas (1); granular cell carcinoma (1); Hashimoto thyroiditis (1); head and neck squamous cell carcinoma (1); hepatocellular carcinoma (1); hereditary renal carcinoma (1); infection (1); melanoma (1); neurological disorders (1); non-small cell lung carcinoma (1); Obesity (1); oral squamous cell carcinoma (1); osteoporosis (1); ovarian carcinoma (1); ovarian serous cystadenocarcinoma (1); spindle cell carcinomas (1); type I diabetes (1).